ALDH1A1 (aldehyde dehydrogenase 1 family member A1)
Diseases named in the same sentence as ALDH1A1 in open-access papers (continued):
Sharing a sentence is not in itself a finding about the gene and the disease.
cancer (continued). "To preliminary clarify the underlying mechanisms, we investigate the correlation between CCR9 and ALDH1A1+cancer stem cells (CSCs), as well as the effect of CCR9 on the migration and invasion of CSCs." (PMID 32308544, 2020). "Further, the metabolic activity of ALDH1A1 is strictly related to inactivation of anti-cancer drugs, including oxazaphosphorines or aldophosphamide, in nontoxic metabolite and the expression of this enzyme is a marker of poor prognosis in many tumors." (PMID 35582039, 2020). "In the present review, we describe the contribution of ALDH1A1 in tumor stemness and cancer progression, analyzing its involvement in angiogenesis, tumor spread, drug-resistance, and immune-evasion." (PMID 35582039, 2020). "Cancer stemness induced via up-regulation of ALDH1A1 and CD44 expression contributes to the acquisition of gefitinib resistance in EGFR-TKI sensitive NSCLC." (PMID 32293355, 2020). "For example, as previously shown, the enzyme ALDH1A1 has been shown to be an attractive target for the induction of adaptive immune responses against cancer." (PMID 32850424, 2020). "DSF/Copper complex was shown to target ALDH1A1 and inhibit cancer recurrence primarily driven by ALDHhigh CSCs." (PMID 32295073, 2020). "Basically, in CC as well as different types of cancer, several reports sustain there is increased presence of ALDH1A1 with respect to normal tissues." (PMID 32766133, 2020). "There is growing evidence supporting the role of ALDH1A1 in cancer invasive phenotype and the ability to metastasize." (PMID 35582039, 2020). "FACS analysis revealed that IL-11 significantly increased the proportion of CD133+ ALDH1A1+ cells, suggesting a role for IL-11 in the regulation of cancer stem cells." (PMID 32686598, 2020). "Another family member, ALDH1A1, was increased in five out of six drug-resistant cell lines and is a marker for cancer stem cells and chemoresistance." (PMID 31344863, 2019). "Our data demonstrate that by fine tuning the levels of intracellular oxidative stress, ALDH1A1, protects cancer cells from DNA damage, enhancing spheroid proliferation and tumorigenicity." (PMID 30965686, 2019). "Several markers are used to identify CSCs in different cancers, and among them, the aldehyde dehydrogenase isoform 1A1 (ALDH1A1) expression analysis is found." (PMID 31412536, 2019). "As a consequence, ALDH1A1 has been selected as a target for anti‐cancer therapy, with ALDH inhibitors shown to reverse chemoresistance in a range of preclinical tumor models." (PMID 30521138, 2019). "Western blot also showed that the expressions of CD44 as well as ALDH1A1, which is another well-known cancer stem cell marker, were repressed in HCC827OR and HCC827GR cells treated with aspirin." (PMID 31993373, 2019). "Drug stress activates β-catenin or Sox2, leading to an increase of ALDH1A1 transcription and enriching cancer stem-like cells; Notch activation by erlotinib also enriches ALDH+ stem-like cells 5-7." (PMID 31695757, 2019). "The correlation coefficient between the expression level of cancer stem cell markers ALDH1A1, CD44, OCT3/4, and ABCG2 with the stages of PTC tumors as well as TFA samples was calculated." (PMID 31341476, 2019). "ALDH1A1, intracellular enzyme with detoxifying role, has been identified as cancer stem cells marker for CC." (PMID 30842790, 2019). "To further evaluate the significance of ALDH1A1 to cancer stemness, we sought to assess the effects of ALDH1A1 knock down to the tumor initiation capacity (TIC) of OC cells." (PMID 30965686, 2019). "ALDH1A1 is an important biomarker for cancer cells and cancer stem cells, and together with ALDH3A1confers resistance to oxazaphosphorines, which include cyclophosphamide in various tumor types." (PMID 30959953, 2019). "Future strategies will focus on the development of second generation ALDH1A1 radiotracers with improved in vivo stability to image drug resistance in animal models of cancer." (PMID 30521138, 2019).
cancer (continued). "The (cancer) stem cell markers ALDH1A1 and LGR5 were expressed at significantly higher in the rounded Wnt active cells." (PMID 31105876, 2019). "CD44 expression decreased by 15% (p < 0.05) in the THYME 1 group and ALDH1A1 expression by 27% (p < 0.05) in the THYME 0.1 group versus the control rat carcinoma cells." (PMID 30970626, 2019). "In the W1 cell line, short-term treatment with PAC upregulated the expression of the ALDH1A1 gene, a marker of Cancer stem cells (CSCs)." (PMID 29649113, 2018). "ALDH1A1, a cytosolic enzyme expressed in several solid tumors, is considered a marker of a subset of cancer stem cells endowed with aggressive traits." (PMID 30541574, 2018). "Because ALDH1A1 has an anti-proliferative role, a low activity of ALDH1A1 can promote cell proliferation and increase the sensitivity of cancer cells to chemotherapy." (PMID 29552329, 2018). "Formation of the inflammation-specific DNA lesion marker 8-nitroguanine was detected in CD44v6- or ALDH1A1-positive cancer cells." (PMID 30340457, 2018). "ALDH expressions, especially the expression of ALDH1A1, are low in atypical teratoid/rhabdoid tumour and cancers from head and neck, breast, and prostate, but high in the rest of cancers." (PMID 29552329, 2018). "Previous studies showed that high ALDH1A1 expression lead to chemotherapy resistance in cancer cell lines." (PMID 31516883, 2018). "These cells, possessing an increase of ALDH1A1 activity, display a number of features such as enhanced capability to form tumorspheres, an indication for the formation of a cancer stem cell niche within the tumor." (PMID 30541574, 2018). "ALDH1A1 is the most popular marker of cancer stem cells (CSCs), and its expression was previously observed by us in PAC- and TOP-resistant cell lines." (PMID 29649113, 2018). "Aldehyde dehydrogenase 1A1 (ALDH1A1) is one of cancer stem cell (CSC) markers, and high ALDH1 expression has been related to drug resistance and facilitated tumor growth." (PMID 30166520, 2018). "Obviously, in this current study, coated NPs were able to inhibit NF-κB expression and ALDH1A1 as well as alter redox balance selectively in cancer cells." (PMID 29545617, 2018). "The inhibiting ALDH1A1 activity and high eliminating the percentage of CSCs lead to missing unique features of cancer cells such as uncontrolled proliferation, self-renewal and drug resistance." (PMID 29545617, 2018). "Many research indicates the role of ALDH1A1 in the cancer biology where increased expression is related to drug resistance in many solid tumors and negatively correlates with progression and overall survival." (PMID 30583585, 2018). "ALDH1A1 was identified as a putative enzyme that converts retinol to retinoic acid in differentiation pathways of normal and cancer stem cells." (PMID 29433490, 2018). "In various experimental models immunotargeting of ALDH1A1 resulted in cancer stem cells eradication, including MSC." (PMID 30486884, 2018). "High levels of aldehyde dehydrogenase 1A1 (ALDH1A1) expression and activity have been proposed as a reliable CSC marker, since they are associated with cancer stem-like features, as cell self-protection, differentiation, expansion, and therapy resistance." (PMID 30541574, 2018). "Our focus on silencing ALDH1A1 was motivated not only because it was abundantly expressed in A549 cells, but also because of its important roles in cancer biology." (PMID 29245909, 2017). "Increased levels of ALDH1A1 and ALDH3A1 in various human cancers have been associated with enhanced tumorigenic ability, chemo-resistance, and poor prognosis." (PMID 28978015, 2017). "Up to now, our and other groups have isolated and characterized ESCC cancer stem-like cells (ECSLCs) using aldehyde dehydrogenase 1A1 (ALDH1A1), CD44, p75NTR and CD90 as markers." (PMID 28431580, 2017). "Our previous work demonstrated that ALDH1A1-positive ESCC cells possess properties of cancer stem-like cells and highly invasive potential." (PMID 28431580, 2017).
cancer (continued). "Aldehyde dehydrogenase 1A1 (ALDH1A1), an intracellular enzyme responsible for detoxifying aldehydes, is a cancer stem-like cell-associated protein in various malignant." (PMID 28431580, 2017). "On the other hand, it has long been established that DSF has inhibitory activity against ALDH, specifically ALDH1A1, and ALDH activity is highly associated with cancer cell stemness." (PMID 28107189, 2017). "Future studies explaining how ALDH1A1/3A1 regulate these downstream genes would help elucidate the exact function of ALDH1A1/3A1 in cancer." (PMID 28978015, 2017). "The ALDH1A1 subpopulation contributes to both tumor initiation and progression and when highly expressed in advanced-stage cancers correlates with poor survival in hormone-naïve patients." (PMID 29259971, 2017). "It has been shown that T-cell lines specific for MHC class I-restricted epitopes of ALDH1A1 can eliminate ALDH1A1 positive cancer cells in HNSCC." (PMID 29112953, 2017). "High expression of ALDH1A1 is found in many cancers and is frequently considered a marker of cancer stem cells." (PMID 28148901, 2017). "Overexpression of C/EBPβ-1 increases transformation, upregulates expression of the cancer stem cell marker ALDH1A1, and leads to chemoresistance." (PMID 28148901, 2017). "All together, these results suggest that inhibition of NRF2 is related with the enhancement of the sensitivity of these cells to chemotherapeutic agents and the expression of cancer cell stemness biomarker as ALDH1A1 and ALDH3A1." (PMID 28671577, 2017). "In general, epithelial cell lines and tumors were associated with cancer stem cell markers (CD24, ALDH1A1, and PROM1), markers of tumor aggressiveness (MYCL1 and ASCL1), and markers of apoptosis (BCL2 and BCL2L11)." (PMID 28212573, 2017). "TM4SF4 knockdown weakened sphere forming and suppressed the expression of cancer stem cell markers such as ALDH1A1, ALDH1A3, Oct3/4, Sox2." (PMID 29254164, 2017). "ALDH1B1, a mitochondrial ALDH, is another promising good prognostic marker for cancer, sharing 65% homology in peptide sequence with cytosolic ALDH1A1 in humans." (PMID 28792511, 2017). "We demonstrated that VX2 tumors have higher expression of cancer stem cell markers such as AlDH1A1 and CD44 in comparison to normal rabbit liver cells." (PMID 26873175, 2016). "This is a major problem in the ALDH/cancer stem cell literature, where ALDH1A1 is often used interchangeably with ALDH1 or ALDH." (PMID 26445849, 2016). "Several reports suggest that CD24, CD44s including CD44v6, and ALDH1A1 are putative markers for cancer stem cells." (PMID 27647953, 2016). "These high invasive sphere-forming cells express aldehyde dehydrogenase 1 family member A1 (ALDH1A1), indicating a possible enrichment of the cancer stem cells." (PMID 27863439, 2016). "Initially, we assessed the expression of Oct4, a marker for pluripotent stem cells, αSMA, a marker commonly expressed by smooth muscle cells but also mesenchymal stromal cells, and ALDH1A1 which is expressed in both normal and cancer stem cell populations." (PMID 27746820, 2016). "This was confirmed by finding that cancer stem cell markers ALDH1A1 and CD133 were upregulated in A2780-DR and A2780-VIM-KN cells that were facile to form spheroids of cells under nutrient deprivation." (PMID 27322682, 2016). "The cytoplasmic ALDH1A1 was elevated in esophageal cells with increasing degrees of dysplasia and in carcinoma in situ." (PMID 26783961, 2016). "Double immunostaining of CD44v6 and ALDH1A1 was occasionally observed in cancer nest cells and the NPC cell line." (PMID 27647953, 2016). "A very recent study performing high-throughput analysis of NMIBC revealed a Class 2 tumor that associates with progression, these Class 2 tumors enriched for cancer stem cell markers such as ALDH1A1, ALDH1A2, PROM1, NES and THY1." (PMID 27655672, 2016). "Recently, one member of the ALDH1 family, ALDH1A1, has been suggested as a marker of stem cells in several cancers, including NPC." (PMID 27647953, 2016).
cancer (continued). "In contrast, ALDH1A1 was stained intensely in the cytoplasm of NPC cancer cells, the same location where 8-nitroguanine was formed in ALDH1A1-positive cells." (PMID 27647953, 2016). "We showed that cancer stem cell markers (AlDH1A1, CD44) and the differentiation marker α-fetoprotein were upregulated in VX2 tumor cells." (PMID 26873175, 2016). "ALDH1A1 overexpression evaluated by IHC has been both correlated with both poor and favorable prognoses in various cancers." (PMID 26783961, 2016). "The expression of CD133, ABCB1, Bcl-2, and ALDH1A1 in the fused cells explains the increased drug resistance of the fused cell, suggesting that the cancer cell would acquire drug resistance through cell fusion with the stem cell." (PMID 26846780, 2016). "Prognostic data on the ALDH1 in various cancers have been accumulated predominantly by using IHC of paraffin embedded cancer tissues with isotype-specific antibodies, ALDH1A1 or ALDH1A3." (PMID 26783961, 2016). "Here we review the functions and mechanisms of ALDH1A1, the key ALDH isozyme linked to SC populations and an important contributor to CSC function in cancers, and we outline its potential in future anticancer strategies." (PMID 26783961, 2016). "ONCOMINE analysis of 6 ALDH1 sub-members in cancer vursus. normal samples showed that ALDH1A1 was significantly downregulated in different types of GC in different datasets." (PMID 27015121, 2016). "Cancer stem cells markers such as ALDH1A1, ABCG2, and nestin are highly expressed in metastatic cancer cells compared to non-metastatic cancer cells in animal models of pancreatic cancer." (PMID 26029109, 2015). "This is contrary to the majority of previous studies which have suggested ALDH1A1 as being the isozyme primarily responsible for the ALDH catalytic activity observed in cancer cells." (PMID 25950950, 2015). "Aldehyde dehydrogenase 1A1 (ALDH1A1) is considered to be a cancer stem cell marker in several human malignancies." (PMID 26160842, 2015). "Detection of the active ALDH1A1 using the AldeFluor assay permitted the identification of several tumor-initiating cell-enriched populations in multiple cancers such as breast, colon, pancreatic, lung, liver and ovarian cancer." (PMID 26244163, 2015). "ALDH1A1 particularly serves as a cancer stem cell marker in several human malignancies, although it also serves as a stem cell marker in somatic stem cells such as hematopoietic stem cells and neural stem cells." (PMID 26160842, 2015). "Aldehyde dehydrogenase 1 family member A1 (ALDH1A1) is a cancer stem cell marker, and its expression correlates with prognosis in a number of malignancies." (PMID 25253129, 2014). "Particularly, ALDH1A1 isozyme has been shown to play an important functional role in maintaining cancer stem cells." (PMID 25216266, 2014). "Recently, ALDH1A1 has gained attention as a putative marker for cancer stem cells and progenitor cells." (PMID 25926859, 2014). "The activation of ALDH1A1 was found in stem cell population in multiple types of cancers including breast, colon, bladder, pancreatic, head and neck squamous, lung, liver and ovarian cancer." (PMID 24676703, 2014). "The current intense interest in ALDH1A1 as a possible marker of cancer stem cells makes understanding its normal distribution and regulation even more imperative." (PMID 25926859, 2014). "On the other hand, an abnormal increase of ALDH1A1 has been observed in certain cancers, while ALDH1A1 inhibitors have been developed for cancer therapy." (PMID 25705376, 2014). "The expression of ALDH1A1 by cancer stem cells can have dire consequences, and this is consistent with our findings." (PMID 24485040, 2014). "Normal cells contain two ALDH1 isoforms, ALDH1A1 and ALDH3A1, but the expression of these proteins has also been associated with drug resistance in cancer stem cells (CSCs)." (PMID 25230277, 2014).
cancer (continued). "Our results demonstrated that the expression of ALDH1A1 and MMP-9 was correlated with each other, indicating higher invasive and metastasizing activity in ALDH1A1 overexpression cancer cells." (PMID 25253129, 2014). "The human Cancer Drug Resistance & Cell Cycle RT2 Profiler PCR Array results were compared between ALDH1A1 knockdown and controls." (PMID 25216266, 2014). "Previous studies in cancer research have identified a number of intracellular signaling pathways that lead to an increase expression of ALDH1A1 in cancer cells." (PMID 25705376, 2014). "Aldehyde dehydrogenase 1A1 (ALDH1A1), one of the characteristic features of tumor-initiating and/or cancer stem cell (CSC) properties, is important in both intrinsic and acquired resistance to gemcitabine." (PMID 24676703, 2014). "A stable shRNA knockdown model for ALDH1A1 was utilized to determine its effect on cancer stem cell-like properties, cell cycle checkpoints, and DNA repair mediators." (PMID 25216266, 2014). "IHC for ALDH1A1 of xenograft tumors revealed that the frequency of ALDH1A1 strongly positive cancer cells was markedly reduced by disulfiram-treatment." (PMID 24194908, 2013). "The results support use of NF-κB as a marker for cancer stem cells because NF-κB and ALDH1A1 levels were strongly correlated." (PMID 23095512, 2012). "ALDH1A1 expression has also been found in a subpopulation of cells with chemoresistance in numerous human cancer types." (PMID 22710732, 2012). "Although in theory CSCs are thought to comprise a small percentage of the cancer cell population, the percentage of high ALDH1A1-staining cells that we found (5.6% to 40.4%)." (PMID 23095512, 2012). "ALDH1A1 is involved in the maintenance of stemness in both normal and cancer stem cells." (PMID 40433700, 2025). "Furthermore, it was showed that overexpression also upregulated the cancer stem cell marker ALDH1A1, which confers resistance to chemotherapy." (PMID 40226120, 2025). "Currently, ALDH1A1-targeted therapy is extensively applied in cancer treatment." (PMID 40093000, 2025). "Notably, cancer cells expressing aldehyde dehydrogenase 1A1 (ALDH1A1), a CSC marker, have been identified as key contributors to poor patient outcomes." (PMID 40076435, 2025). "Furthermore, we discovered that a low dose of NU7441 significantly reduced CSC enrichment in drug-resistant cancer cells, as shown by decreased expression of key markers of CSCs (ALDH1A1, KLF4, CD133, Nanog, and SOX9) and diminished sphere formation ability." (PMID 41272697, 2025). "Additionally, results for other drug sensitivity markers (ABCG2, ABCB1, BCL2; P < 0.00001) and cancer stem cells (CSCs) markers (ALDH1A1, PROM1; P < 0.01) were also presented." (PMID 40264043, 2025). "This survival data further showed that ALDH1A1 likely participates in the distinct rexinoid pathway, as high expression of ALDH1A1 predicted better outcomes in both ER-positive and ER-negative cancers, consistent with decreased tumor growth after ALDH1A1 overexpression in mouse models." (PMID 41210994, 2025). "Adding to this fact is the observation that the cancer stem cell marker ALDH1A1 is underexpressed in AML cells when compared to healthy cells, both at the RNA level and at the protein level, and at least in regard to the RNA level, both in the bone marrow and in peripheral blood." (PMID 40643557, 2025). "Regardingly, ALDH1A1 expression was found to be significantly upregulated in the high stemness group compared to the low stemness group as revealed through bioinformatics analysis, and positively correlated with cancer stemness." (PMID 40886002, 2025). "We examined the expression of ALDH1A1, a core marker of cancer stem cells (CSCs)." (PMID 41383473, 2025). "ALDH1A1's prognostic significance varies across different cancers." (PMID 39744576, 2025).